RNU6-274P (RNA, U6 small nuclear 274, pseudogene)
Gene: Small nuclear RNA gene on chromosome 7 (89,754,620 to 89,754,726, reverse strand). Ensembl gene ENSG00000239075.
Homologues: Orthologues: chimpanzee U6 (100% identical), chimpanzee U6 (99% identical), macaque U6 (89% identical), pig U6 (78% identical), mouse Gm24875 (74% identical). Paralogues in human: RNU6-1145P (88% identical), RNU6-393P (88% identical), RNU6-1316P (87% identical), RNU6-20P (87% identical), RNU6-35P (87% identical), RNU6-41P (87% identical), RNU6-434P (87% identical), RNU6-686P (87% identical), RNU6-1075P (86% identical), RNU6-1181P (86% identical), RNU6-1209P (86% identical), RNU6-16P (86% identical), and 1287 more.